HSP90AB1 (heat shock protein 90 alpha family class B member 1)
Diseases named in the same sentence as HSP90AB1 in open-access papers (continued):
Sharing a sentence is not in itself a finding about the gene and the disease.
lung adenocarcinoma (10 papers, 2016 to 2025). A carcinoma that arises from the lung and is characterized by the presence of malignant glandular epithelial cells. "The expression of HSP90AB1 also caused the worse prognosis in lung adenocarcinoma." (PMID 34712697, 2021). "Phosphorylation of HSP90AB1 at Ser255 was found to be associated with lung adenocarcinoma." (PMID 33931671, 2021). "Consistent with this, high expression of HSP90AA1 and HSP90AB1 was significantly correlated with poorer prognosis of patients suffering from lung adenocarcinoma." (PMID 36982267, 2023). "The positive expression rate of Hsp90AB1 in lung adenocarcinoma tissues (61.2%) was significantly higher than that in lung squamous cell carcinoma tissues (37.9%)(P=0.002), and its over-expression was associated with poor prognosis in lung adenocarcinoma patients (P=0.032)." (PMID 26903158, 2016). "In addition, EEF1A2 interacts with HSP90AB1 to promote lung adenocarcinoma metastasis, and DSCC1 interacts with HSP90AB1 to enhance the proliferation and metastasis of lung adenocarcinoma cells." (PMID 41209079, 2025).
melanoma (10 papers, 2012 to 2024). A malignant, usually aggressive tumor composed of atypical, neoplastic melanocytes. "Based on correlation analysis between PDC6IP and 83 MTEX proteins differentiating melanoma patients with PD from those with NED/SD, we found four proteins that strongly (ru > 0.7, P < 0.005) associated with PDC6IP, namely HSP90AB1, PFN1, TUBB, and TUBB1." (PMID 33613873, 2021). "By means of ROH island analyses, we identified the genes SPRY4, NDFIP1, IMPDH2, HSP90AB1, which might play an important role for further studies on equine melanoma." (PMID 30836959, 2019). "Under standard conditions (37 °C), melanoma cells were characterized by a high level (>0.04) of HSPD1 (HSP60), HSPA8 (HSP70), and HSP90AB1 (HSP90), and a medium level (0.02–0.04) of HSPB1 (HSP27), HSPA9 (HSP70), and AHSA1 (HSP90)." (PMID 37886980, 2023). "From this, we identified a panel of 6 genes, ALDH1A1, HSP90AB1, KIT, KRT16, SPRR3 and TMEM45B whose expression values discriminated metastatic from primary melanoma (87% classification accuracy)." (PMID 29229936, 2017). "ROH island analyses identified several annotated genes (SPRY4, NDFIP1, HSP90AB1 and IMPDH2), which may play a role for further studies on equine melanoma." (PMID 30836959, 2019). "Hence, the molecular signature of MTEX consisting of PDCD6IP/ALIX, 4 correlated proteins (HSP90AB1, TUBB, TUBB1, and PFN1) highly expressed in MTEX of patients with PD, plus CNTN1 and TGF‐β1 with differential distribution in MTEX of PD vs NED/SD patients may have prognostic significance in melanoma." (PMID 33613873, 2021).
prostate carcinoma (9 papers, 2016 to 2025). A carcinoma that arises from epithelial cells of the prostate gland. "In addition, we explored therapeutic targets by investigating FOXA1 interacting protein within proteins encoded by upregulated genes in FOXA1 mutant prostate cancer, and identified six genes—HSP90AB1, KDM1A, FKBP4, H2BC15, WNT7B, and GRB7." (PMID 37958805, 2023). "In Prostate cancer pathway, HSP90AB1 and HSP90B1 can indirectly affect cell proliferation and survival by activating Ar and thus binding to DNA sites." (PMID 38280998, 2024). "Lastly, HSP90AB1 was included in five pathways, such as “Pathways in Cancer” and “Prostate Cancer”." (PMID 40230723, 2025).
diabetes (8 papers, 2018 to 2024). "In our current study, we thus prioritized HSP90AB1 inhibition, which had been shown to improve skeletal muscle mitochondrial metabolism in a diabetes mouse model." (PMID 38727583, 2024). "Knockdown Hsp90ab1 in the mouse model of diabetes demonstrated the key role of this gene in controlling diabetes-mediated signaling pathways such as glucose metabolism and insulin signaling." (PMID 38931172, 2024). "HSP90AB1 has been identified as a potential therapeutic target for metabolic diseases including diabetes, and suppression of HSP90AB1 is a valid therapeutic clinically relevant strategy in the management of dysregulated metabolic disease and insulin resistance." (PMID 35885938, 2022). "HSP90AB1 may serve as a potential new target for the treatment of metabolic diseases, including diabetes." (PMID 35885938, 2022). "Hsp90ab1 represents a novel target for potential treatment of metabolic disease including diabetes." (PMID 29434648, 2018). "Moreover, we prioritized drug-targets such as melatonin, resveratrol, eugenol, lapatinib, geldanamycin and azathioprine which interacted with ESR1, ERBB2, HSP90AB1 and RAC1, respectively and shown associations in diabetes treatment in experimental models of T1D." (PMID 33841528, 2020). "Thus, HSP90ab1 represents an actionable target that could translate into potential therapeutic benefit for diabetes." (PMID 29434648, 2018).
glioma (8 papers, 2015 to 2025). A benign or malignant brain and spinal cord tumor that arises from glial cells (astrocytes, oligodendrocytes, ependymal cells). "An integrated omics analysis predicted HSP90AB1 as a key HSP in glioma." (PMID 42135822, 2025). "MAPK3 and CX3CL1 were strongly positive; NFE2L2, HSP90AB1, and SUPT20H were moderately positive; and FKBP1B, BIRC5, NPC1, IKBKE, BID, and PTEN were weakly positive in glioma tissue relative to their expression levels in normal tissue." (PMID 33194668, 2020).
osteosarcoma (7 papers, 2004 to 2026). A usually aggressive malignant bone-forming mesenchymal neoplasm, predominantly affecting adolescents and young adults. "In osteosarcoma studies, it is reported that the transcript levels of ENO1, MSN, and HSP90AB1 were higher in osteosarcoma tissues than in normal tissues." (PMID 37894284, 2023). "Regarding Hsp90ab1 (aka Hsp90b), it is shown in osteosarcoma cells that secreted Hsp90ab1 proteins inhibit the activation of latent TGFβ." (PMID 36810561, 2023). "And there were 38 endogenous genes (including ARF1, HSP90AB1, and TUBA1B), 53 TFs (including E2F1, NFKB1, and EGR1), and 858 ncRNAs (including MALAT1, miR-590-3p, and TUG1) were considered as key regulators of osteosarcoma through a series of function enrichment analysis and network analysis." (PMID 30936265, 2019).
viral infection (7 papers, 2014 to 2025). "Apoptosis-related genes such as ced-10 and heat shock proteins (hsc71, Hsp60A, and HSP90AB1) were also upregulated in clusters 0 and 6, indicating their involvement in programed cell death during viral infection." (PMID 40679295, 2025).
colorectal cancer (6 papers, 2016 to 2025). A primary or metastatic malignant neoplasm that affects the colon or rectum. "Our findings indicate that the C allele of the novel colorectal cancer-associated variant rs2282151 is associated with increased expression levels of HSP90AB1, which is expressed higher in colorectal tumor tissues than in normal tissues." (PMID 27756247, 2016). "Evidence suggests that HSPA4, HSP90AB1, DNTM1, RPS27, FTL, NCL, A2M are implicated in the pathogenesis and progression of colorectal cancer, positioning them as potential prognostic biomarkers for the onset of metastasis." (PMID 41319168, 2025). "Together, in this study we demonstrate that the constitutively expressed heat shock factor HSP90AB1 is highly dependent upon USP22-mediated epigenetic regulation in human breast and colorectal cancer cell lines as well as in murine mammary and colorectal tumors." (PMID 31801945, 2019).
COVID-19 (6 papers, 2021 to 2024). A disease caused by infection with severe acute respiratory syndrome coronavirus 2. "In the COVID-19 group, the DEPS with the highest number of edges were MAPK1, MAP2K1, HSP90AB1, and FN1." (PMID 39301288, 2024). "HSP90AB1, a member of the HSP90 family, is involved in the immune and inflammatory responses to COVID-19, ASFV, and PDCoV." (PMID 37511286, 2023). "The potential mechanism of action of HXZQ for COVID-19 is inhibiting SARS-CoV-2 replication, improving immune, and anti-inflammatory, mainly by acting on 3CLpro, PTGS2, AR, HSP90AB1, CAMSAP2, PPARG, NOS2, and other targets." (PMID 36388945, 2022). "These compounds may interfere with ACE2 binding to PTGS2, HSP90AB1, AR, CAMSAP2, and other targets that regulate multiple signaling pathways and thus exert a preventive or therapeutic effect on COVID-19." (PMID 34335247, 2021).
lymph node metastasis (6 papers, 2012 to 2022). "Hsp90ab1 protein expression level was positively associated with lymph node metastasis (χ2 = 23.421, P < 0.001), vascular invasion (χ2 = 4.343, P < 0.05), American Joint Committee on Cancer (AJCC) stage (χ2 = 17.889, P < 0.001) and T stage (χ2 = 6.313, P < 0.05)." (PMID 30305727, 2019). "Further statistical analysis revealed that the mRNA expression of AHA1, but neither Hsp90aa1 nor Hsp90ab1, is significantly correlated with the clinicopathological characteristics such as TNM stage (p = 0.035), lymph node metastasis (p = 0.012), and metastasis (p = 0.0003)." (PMID 34620942, 2021).
ovarian carcinoma (6 papers, 2019 to 2023). A malignant neoplasm originating from the surface ovarian epithelium. "As a traditional Chinese medicine, ME can prevent ovarian tumors and cause DNA damage to induce ovarian cancer cell apoptosis by inhibiting HSP90AB1/IGF1R." (PMID 37180757, 2023). "Thus, inhibition of cisplatin-induced DNA damage by HSP90AB1 overexpression is an important cause of resistance to chemotherapy in ovarian cancer, and ME can reverse cisplatin resistance by inhibiting HSP90AB1." (PMID 37180757, 2023). "Collectively, these data demonstrate that ME treatment increases the sensitivity of ovarian cancer cells to cisplatin by suppressing HSP90AB1 expression, thereby inhibiting the proliferation, invasion, and migration of ovarian cancer cells." (PMID 37180757, 2023). "Our current study suggests that the suppression of HSP90AB1 by ME enhances the sensitivity of ovarian cancer cells to cisplatin, suggesting that inhibition of HSP90AB1 by ME contributes to DNA damage and apoptosis in ovarian cancer cells." (PMID 37180757, 2023). "We also found that apoptosis-related genes, URI1, PAK2, PARP1, CLU and TIMP3, were highly expressed, while immune-related genes, UBB, RPL11, CAV1, NUPR1 and Hsp90ab1, were lowly expressed in ovarian cancer cells." (PMID 37124501, 2023). "RT-qPCR analysis revealed that URI1, PAK2, PARP1, CLU, and TIMP3 were significantly upregulated, while UBB, RPL11, CAV1, NUPR1, and Hsp90ab1 were significantly downregulated in the ovarian cancer samples." (PMID 37124501, 2023). "Significantly, HSP90AB1, a prognostic marker of ovarian cancer, was highly expressed in both A2780 and A2780/CDDP cells." (PMID 37180757, 2023). "HSP90AB1 is a new molecular marker for chemotherapy resistance and might serve as a new drug target for ovarian cancer chemotherapy." (PMID 37180757, 2023). "In turn, inhibition of HSP90AB1 further promotes ME-induced ovarian cancer cell apoptosis." (PMID 36362498, 2022). "This set includes eight SASP proteins, for example, 14‐3‐3 protein β/α (YWHAB) and HSP90AB1, which may play a role in apoptosis and inflammation and is a tissue‐specific biomarker of survival in ovarian cancer." (PMID 33512769, 2021). "Our study found that ME treatment effectively reversed HSP90AB1 overexpression, downregulated the expression of cancer-related factors IGF1R and MYC, and exerted anti-tumorigenic effects in ovarian cancer." (PMID 36362498, 2022). "RNA sequencing combined with bioinformatics analysis showed that HSP90AB1 and IGF1R, two known drug-resistance genes, are overexpressed in A2780/CDDP cells, and we found that HSP90AB1 promotes IGF1R expression in ovarian cancer cells." (PMID 37180757, 2023).
glioblastoma (5 papers, 2015 to 2024). The most malignant astrocytic tumor (WHO grade IV). "They did however find higher expression of HSP90AA1 and HSP90AB1 in the recurrent glioblastomas." (PMID 36358853, 2022).
Insulin resistance (5 papers, 2018 to 2024). Increased resistance towards insulin, that is, diminished effectiveness of insulin in reducing blood glucose levels. "Together, these data demonstrate that Hsp90ab1 is a key regulator of skeletal muscle metabolism and represents a viable therapeutic target for management of insulin resistance and metabolic disease." (PMID 29434648, 2018). "The present study demonstrates that Hsp90ab1 is a regulator of skeletal muscle metabolism and suppression of Hsp90ab1 is a valid therapeutic clinically relevant strategy in the management of dysregulated metabolic disease and insulin resistance." (PMID 29434648, 2018).
metastatic tumors (5 papers, 2023 to 2025). "PHB2 and HSP90AB1 were overexpressed in the metastatic tumors compared with LUAD primary tumors, and high level of HSP90AB1 predicted shorter overall survival and first progression times of LUAD patients." (PMID 37742009, 2023). "In addition to these molecular alterations, amplification of MYC, HSP90AB1, and VEGF-A and mutation of GRIN2A were present in the metastatic tumors." (PMID 38837109, 2024). "While MYC amplification was an acquired molecular event (included in the NGS panel used for the initial and metastatic tumor), it is not clear whether HSP90AB1, VEGFA, or GRIN2A were present at the time of initial diagnosis." (PMID 38837109, 2024). "Thus, it is reasonable that the low expression of HSP90AB1 and MME in metastatic but not primary tumor samples and the low RPS6KB1 expression in primary but not metastatic tumor samples are correlated with prolonged survival." (PMID 38578805, 2024).
non-small cell lung carcinoma (5 papers, 2016 to 2025). A group of at least three distinct histological types of lung cancer, including non-small cell squamous cell carcinoma, adenocarcinoma, and large cell carcinoma. "The aim of this study is to detect the expression of Hsp90AB1 in non-small cell lung cancer (NSCLC) tissues, and explore its clinical significance." (PMID 26903158, 2016).
Obesity (5 papers, 2013 to 2024). Accumulation of substantial excess body fat. "Moreover, HSP90AB1 is located near the obesity SNP, rs6905288." (PMID 24455749, 2013). "In these studies mRNA expression of Hsp90ab1, Hsp90aa1, Hsp90b1, and TRAP1 were assessed from skeletal muscles of mice fed a high fat diet (diet-induced obesity, DIO) and compared to lean counterparts." (PMID 29434648, 2018). "Using the same method, seven highly ranked genes (BAP1, GRB14, HSP90AB1, ITGA5, NCKAP5L, SP1, and TOMM5) within ±1 Mb of obesity SNPs were identified." (PMID 24455749, 2013).
pulmonary fibrosis (4 papers, 2020 to 2023). Chronic progressive interstitial lung disorder characterized by the replacement of the lung tissue by connective tissue, leading to progressive dyspnea, respiratory failure, or right heart failure. "We highlight the presence in our analysis of the HSP90AB1, a known chaperone that facilitates the maturation of a wide range of proteins and its attenuation has been related to idiopathic pulmonary fibrosis and cystic fibrosis." (PMID 32974353, 2020).
asthma (3 papers, 2019 to 2025). "Immune infiltration analysis further supported the relevance of these targets, linking HSP90AB1 and ERBB2 expression to M2 macrophage polarization and highlighting asthma-specific immune dysregulation." (PMID 41403444, 2025). "Critically, NR3C1, HSP90AB1, and ERBB2 collectively suppress plasma cells (unified negative correlations), implicating synergistic control of humoral immunity dysregulation in asthma." (PMID 41403444, 2025). "Despite these limitations, our study identifies seven core targets (HSP90AB1, CCNB1, CCK, CDK6, CASP9, NR3C1, and ERBB2) that offer promising avenues for developing novel asthma therapies." (PMID 41403444, 2025). "Fructus Xanthii exerts anti-asthmatic effects by modulating HSP90AB1/IL6/TNF and PI3K-AKT pathways, regulating inflammation, cell cycle, apoptosis, and immune homeostasis, providing empirical support for multi-target traditional Chinese medicine strategies in asthma management." (PMID 41403444, 2025).
atherosclerosis (3 papers, 2024 to 2025). A disease characterized by the build-up of fatty material and calcium deposition in the arterial wall resulting in partial or complete occlusion of the arterial lumen. "The “Lipid and Atherosclerosis” pathway highlights HSP90AB1, IRAK4, and JAK2, which are associated with lipid metabolism and immune responses." (PMID 40621499, 2025).
fatty liver (3 papers, 2019 to 2024). "Several studies suggest that heat shock protein 90β (HSP90β, encoded by HSP90AB1) is closely related to liver steatosis." (PMID 38342927, 2024).
glaucoma (3 papers, 2019 to 2025). Increased pressure in the eyeball due to obstruction of the outflow of aqueous humor. "HSP90AB1, RCOR3, SCAMP2 and SLC64A (AUC < 0.8) showed poor ability to distinguish POAG from non-glaucoma individuals." (PMID 37940950, 2023).
hyperlipidemia (3 papers, 2022 to 2025). "HSP90AB1 demonstrated good diagnostic accuracy in the nephrolithiasis validation cohort (AUC = 1.000) and in the hyperlipidemia validation cohort (AUC = 0.880)." (PMID 40245021, 2025). "Ultimately, the best common diagnostic biomarkers for nephrolithiasis and hyperlipidemia were identified as 3 diagnostic genes (HSP90AB1, HSPA5 and STUB1)." (PMID 40245021, 2025). "Our study suggests that HSP90AB1 is a potential diagnostic target for patients with hyperlipidemia and kidney stones, a conclusion that is partially supported by previous research." (PMID 40245021, 2025). "The expression of HSP90AB1 was lower in both the nephrolithiasis group (P<0.01) and the hyperlipidemia group (P<0.0001)." (PMID 40245021, 2025). "The same ROC analysis was performed for the hyperlipidemia group, with HSP90AB1 (AUC=0.777), HSPA5 (AUC=0.838), and STUB1 (AUC=0.877) also showing robust predictive performance." (PMID 40245021, 2025). "Based on the results of immune infiltration, we speculate that HSP90AB1 may contribute to hyperlipidemia by modulating monocyte activation and inflammatory responses." (PMID 40245021, 2025). "In addition, we validated the reliability of HSP90AB1, HSPA5, and STUB1 as diagnostic genes for nephrolithiasis and hyperlipidemia through external validation." (PMID 40245021, 2025).
lung disease (3 papers, 2021 to 2022). "Patients with lung disease have a higher level of cytoplasmic HSP90 homologs (HSP90AA1 and HSP90AB1) in relationship to mitochondrial HSP90 homolog (TRAP1), whereas patients with lung cancer have a higher level of TRAP1 to the level of cytoplasmic HSP90." (PMID 34692733, 2021).
lymphoma (3 papers, 2022 to 2023). A malignant (clonal) proliferation of B- lymphocytes or T- lymphocytes which involves the lymph nodes, bone marrow and/or extranodal sites. "The effects of artesunate-induce inhibition on the expression of Hsp90aa1, Hsp90ab1, and associated client proteins (AKT, p-AKT, ERK, p-ERK, and EGFR) were investigated in the malignant lymphoma cell lines Daudi and CA-46 using western blotting." (PMID 37719860, 2023).
pancreatic cancer (3 papers, 2019 to 2023). "High expression levels of HSP90AA1 and HSP90AB1 (associated with a low MZF1 expression scenario) were significantly correlated with poorer prognosis of patients suffering from pancreatic cancer." (PMID 36982267, 2023). "Recently, it was proposed that Hsp90ab1 might stabilize Cdc25A, increasing its expression levels and promoting cell-cycle activation in pancreatic carcinoma cells." (PMID 30305727, 2019).